CD1A (CD1a molecule)
Diseases named in the same sentence as CD1A in open-access papers (continued):
Sharing a sentence is not in itself a finding about the gene and the disease.
cancer (continued). "In our study, CD1a, CD207, and CD303 were selected based on previous studies investigating different malignant neoplasms and the biological behavior of such markers." (PMID 31880289, 2020). "Laricitrin treatment stimulated DC differentiation and maturation in the condition media of cancer cells, a finding supported by monocyte marker CD14's disappearance and DC marker CD1a's upregulation." (PMID 27833081, 2016). "Conversely, some genes that displayed anti-HIV activity are known to be involved in signaling, both in various cancers (CD164, TNFRSF10A/D, ZWINT, MT1X, IL3) and immune or T cell activation (GBP5, CD1A)." (PMID 25980612, 2015). "Additionally, by stimulating cancer cells to release inflammatory chemokines (CCL2 or CCL20), IL-17A-producing cells can enhance CD1a+ DC infiltration of the TME, which is correlated with favorable OS of patients with ESCC." (PMID 33995371, 2021). "Considering CD1A is an immune regulatory gene and CCNA1 is involved in response pathways to HPV infection, it is plausible that these genes would play a larger role in more antigenic cancers with a viral etiology." (PMID 26518708, 2015). "The lower expression of CD1a is probably not of any functional importance in the context of mRNA loaded DC to be used as cancer vaccines, since this molecule functions to present bacterial lipids to T cells." (PMID 17608923, 2007). "We initially considered that LN infiltration by CD1a-DCs would be associated with favorable clinical outcomes and that if CD1a-DCs migrated into regional LNs from the primary site, there would be CD1a-DCs in not only metastatic LNs but also in LNs without cancer metastasis." (PMID 39684473, 2024). "CD1A can bind both self and non-self lipid and glycolipid antigens and presents these antigens to T-cell receptors found on natural killer lymphocytes and T lymphocytes, providing crucial assistance in detecting and responding to foreign invaders, including cancer cells." (PMID 38275392, 2023).
infection (31 papers, 2012 to 2025). The state of being infected such as from the introduction of a foreign agent such as serum, vaccine, antigenic substance or organism. "Upon cell sorting of the three moDC subsets and HCMV-NG exposure, the CD1a−/CD86− subset (M1) again showed higher infection susceptibility than CD1a+ cells (M2)." (PMID 38409141, 2024). "It is definite that Leishmania parasites interact and infect a variety of host cell types, CD68+ macrophages and CD1a DCs are the most important cells that regulate the outcome of infection." (PMID 29515633, 2017). "Before infection, the immature DC phenotype (CD1a +, HLA-DR +, CD80 −, CD86 −, CD14 −, CD83−) was verified by flow cytometry (Figure A1)." (PMID 23970881, 2013). "Infection levels (% p24 + of CD1a + cell fraction) varied from 1.3 to 6.6%." (PMID 36841916, 2023). "CD1a has been shown to present mycobacterial antigens from the cell surface where it interacts with langerin on Langerhans cells, a specialized dendritic cell type that surveys epithelial monolayers for molecular indicators of infection." (PMID 33528563, 2021). "While CD1a is constitutively expressed on epidermal Langerhans cells, CD1b is normally rare in the skin, but has been shown to be upregulated in the dermis after infection with Borrelia burgdorferi." (PMID 34914694, 2021). "We speculate that, when monocytes migrate to the infection site, they interact with components of the fungal cell wall, especially α-glucans, and undergo an inadequate differentiation into CD1a– DCs." (PMID 31736892, 2019). "This suggests that, even though group 1 CD1-restricted T cells may help to protect the host from TB by producing IFN-γ, specific CD1a–c-restricted subsets of these cells may respond to the same infection in different ways." (PMID 30319649, 2018). "Importantly, Mtb-infected MoDCs, but not uninfected cells, could present this antigen to activate the CD1a-restricted reporter line, confirming that didehydroxymycobactin is naturally processed and presented during infection." (PMID 40709176, 2025). "However, upon trauma, infection or any form of barrier breach, these antigens could gain access to LC and increase the response of CD1a-autoreactive T cells." (PMID 26284072, 2015). "(A, B) The emigrating cells were harvested and stained with (A) anti-CD1a and anti-HIV-1 mAbs for DCs, and (B) anti-CD3, anti-CD4, and anti-HIV-1 mAbs for CD4+ T cells and the level of infection was assessed by flow cytometry (N = 7–8)." (PMID 32876566, 2020). "Langerhans cell populations getting depleted over the chronicity of the infection due to exhaustion of antigen presentation could also be a reason for not having CD1a-stained amastigotes in patients with high parasite loads." (PMID 39523649, 2024). "To investigate whether GAS can exacerbate skin inflammation through CD1a in vivo, we intradermally challenged CD1a-Tg and wild-type mice with live GAS to the ear skin and the skin inflammation was assessed at day 1 and day 8 post-infection." (PMID 37267382, 2023). "The immune cells were stained with (C–D) anti-CD1a and anti-HIV-1 mAbs for DCs, (E–F) anti-CD163 and anti-HIV-1 mAbs for macrophages (G–H), and anti-CD3, anti-CD4, and anti-HIV-1 mAbs for CD4+ T cells and the level of infection was assessed by flow cytometry (N = 11–15)." (PMID 32876566, 2020). "Data presented here in septic patients with amplified populations of CD1a−negative and regulatory CD1a+ DC may therefore result from the combined effects of infection and stress." (PMID 23071758, 2012). "The availability of validated antibodies for rhesus enabled characterization of infected leucocyte subsets, including "inflammatory" monocytes expressing CD14/CD68, dendritic cell phenotypes with CD1a/DCSIGN positivity, but no intracellular infection of T-cells, or endothelial cells was found." (PMID 29522521, 2018).
infection (continued). "In addition, HIV-1 negative factor (Nef) downregulates CD1a after infection of immature DCs with HIV-1 and impairs stimulation of CD1a-restricted T cells." (PMID 29616036, 2018).
infectious disease (4 papers, 2011 to 2024). A disorder directly resulting from the presence and activity of a microbial, viral, or parasitic agent in humans. "Group 1 CD1 (CD1a, CD1b, and CD1c)-restricted T cells have been implicated to play critical roles in a variety of autoimmune and infectious diseases." (PMID 26175733, 2015). "Further review of the ‘immune response’ GO cluster and genes within this category (CD1A, CD80, CD86, and HLA-DQB1) revealed related pathways which were in the same biological process associated with numerous autoimmune and infectious diseases." (PMID 38448477, 2024). "Of particular note is the finding that CD1a is up-regulated in vitro by G4 more vigorously in MOs obtained from MS patients bearing an infectious disease, with respect to MOs obtained from noninfected MS patients." (PMID 21603161, 2011). "The immunohistochemistry results suggested that these cells were S-100-positive, CD68-positive, and CD1a-negative; staining with GMS and PAS was negative, thereby excluding infectious diseases, which aids in differentiating RDD from other diseases." (PMID 28770226, 2017).
adenocarcinoma (2 papers, 2023 to 2024). A common cancer characterized by the presence of malignant glandular cells. "Only DC CD1a+ and CD1c+ infiltrated adenocarcinomas’ glandular epithelium, the former in higher numbers (Me: 75; IQ: 41–119)." (PMID 36768258, 2023).
bacterial infection (2 papers, 2018 to 2023). "This suggests that GAS can drive a CD1a-dependent auto-reactive T cell response, allowing LPC to act as a signal of tissue damage in response to bacterial infection." (PMID 37267382, 2023).
benign neoplasm (1 paper, 2016). A neoplasm which is characterized by the absence of morphologic features associated with malignancy (severe cytologic atypia, tumor cell necrosis, and high mitotic rate). "Simple STRDD is an unknown benign neoplasm and is mainly confirmed by pathological examinations, showing positive for S-100 protein and CD68, and negative for CD1a." (PMID 27442634, 2016).
neurodegenerative disease (1 paper, 2019). A disorder of the central nervous system characterized by gradual and progressive loss of neural tissue and neurologic function. "Given the potential effects of these variants, CD1A should be further investigated as a gene of interest in neurodegenerative diseases and as a potential target for monitoring disease trajectories and treating disease." (PMID 31295725, 2019). "The CD1A should be further investigated as a gene of interest in neurodegenerative diseases and as a potential target for monitoring disease trajectories and treating disease." (PMID 31295725, 2019). "In summary, previous studies have indicated that the CD1A-related immune activation and peripheral inflammation may be important mechanisms contributing to neurodegenerative diseases." (PMID 31295725, 2019). "Moreover, previous studies suggested that anti-CD1a antibody can reduce inflammation, indicating that blocking the interaction of CD1a with receptors on T cells could be a potential treatment for neurodegenerative diseases." (PMID 31295725, 2019).
CD1A also shares sentences with these, for which no sentence is quoted: Allergy (2 papers); B‐cell chronic lymphocytic leukaemia (2); contact dermatitis (2); cutaneous leishmaniasis (2); ductal carcinoma in situ (2); fibrosis (2); germinoma (2); gingivitis (2); histiocytic neoplasm (2); histiocytic sarcoma (2); Insulin resistance (2); invasive ductal carcinomas (2); neoplastic disorder (2); squamous cell carcinoma (2); T-cell lymphoma (2); vitiligo (2); abortion (1); acinar cell carcinoma (1); allergic contact dermatitis (1); autoimmune disease (1); B-cell lymphomas (1); benign lymphoid hyperplasia (1); benign melanocytic nevus (1); carcinosarcoma (1); cerebral autosomal recessive arteriopathy with subcortical infarcts and leukoencephalopathy (1); cervical squamous cell carcinoma (1); chondroid syringoma (1); chronic lymphoid leukemia (1); chronic respiratory failure (1); chronic thyroiditis (1).
A further 78 diseases each share a sentence with CD1A in 1 paper.